PTH (parathyroid hormone)
Diseases named in the same sentence as PTH in open-access papers (continued):
Sharing a sentence is not in itself a finding about the gene and the disease.
secondary hyperparathyroidism (continued). "This study provides important findings concerning the delayed fracture healing of the patient with primary or secondary hyperparathyroidism, and might improve our understanding of the appropriate interval of PTH administration for bone fracture management." (PMID 30181648, 2018). "Raised parathyroid hormone may suggest secondary hyperparathyroidism as a result of receptor resistance to the hormone.This patient continued to have a poor prognosis as is normally the case with infantile OP." (PMID 30505439, 2018). "Alternatively, PTH has been shown to have direct effects on the endothelial expression of vascular endothelial growth factor such that worsening secondary hyperparathyroidism could be driving increased perfusion." (PMID 29955640, 2018). "However, 51% remained deficient, and in three infants, there was potentially clinically important secondary hyperparathyroidism, serum PTH values between 12.6 and 29.5 pmol/L (upper limit normal 7 pmol/L)." (PMID 29342867, 2018). "It has also been shown that PTH is closely related to cognitive function and that cognitive function can be improved after parathyroidectomy in patients with secondary hyperparathyroidism, suggesting that renal dysfunction-induced accumulation of PTH affects cognitive function in CKD patients." (PMID 30429775, 2018). "In fact, as 1,25(OH)2D value is finely regulated, a low vitamin D status may induce 1,25(OH)2D parathyroid hormone (PTH)-related increase following secondary hyperparathyroidism, with normal or even elevated 1,25(OH)2D levels." (PMID 29914099, 2018). "We reported a much higher prevalence of secondary hyperparathyroidism compared with other studies, 41 which could be due to using lower PTH cut-off point to define secondary hyperthyroidism or using different laboratory methods to measure PTH." (PMID 30068613, 2018). "If we used the reference range of the laboratory where the samples were tested (PTH: 1.3–9.3 pmol/L), the prevalence of secondary hyperparathyroidism would be 32.56%, 12.35% and 11.68% among adolescents with vitamin D severe deficiency, deficiency and insufficiency, respectively." (PMID 30068613, 2018). "First, distinct models of continuous hyperparathyroidism were employed: The mechanisms that control bone loss in primary hyperparathyroidism (mimicked to some degree by PTH infusion) may be different than those operant in secondary hyperparathyroidism." (PMID 30283888, 2018). "The PTH role in a broad spectrum of vascular disorders such as coronary microvascular dysfunction, vascular calcification, increased vascular stiffness, and blood pressure is a well-established concept, in both primary and secondary hyperparathyroidisms." (PMID 30662585, 2018). "It would also be necessary to check parathyroid hormone levels in vitamin D deficient subjects to rule out secondary hyperparathyroidism because serum calcium, phosphorous and alkaline phosphates were normal levels among vitamin D deficient subjects." (PMID 30344585, 2018). "Persistently low levels of vitamin D might lead to a mineralisation defect (osteomalacia) and a compensatory parathyroid hormone (PTH) increase (secondary hyperparathyroidism." (PMID 28774221, 2017). "The secondary hyperparathyroidism would influence the postoperative PTH level in VDD patients." (PMID 29100453, 2017). "Secondary hyperparathyroidism (SHPT), a common serious and progressive complication associated with chronic kidney disease (CKD), is characterized by persistently elevated serum parathyroid hormone (PTH), parathyroid gland (PTG) hyperplasia and mineral metabolism abnormalities." (PMID 28811539, 2017). "Additionally, marrow fibrosis has been reported in cases of primary and secondary hyperparathyroidism with very high levels of PTH." (PMID 27506667, 2016).
secondary hyperparathyroidism (continued). "Since oestradiol status may affect parathyroid hormone action in primary hyperparathyroidism and PTH values in secondary hyperparathyroidism studies were confined to men who are a relatively understudied group in CD." (PMID 27672477, 2016). "Cinacalcet may improve anemia in chronic hemodialysis patients with secondary hyperparathyroidism, possibly through pathways both within and outside the parathyroid hormone pathways." (PMID 27764168, 2016). "Our findings are consistent with the hypothesis, based on the findings of basic science papers, that blockage of high parathyroid hormone levels may improve anemia in patients with secondary hyperparathyroidism." (PMID 27764168, 2016). "Coincidentally, a similar phenomenon was reported not long after the post-marketing of cinacalcet which is a calcimimetic compound used to suppress parathyroid hormone secretion from parathyroid glands in both primary hyperparathyroidism and secondary hyperparathyroidism." (PMID 25775025, 2015). "Similarly, studies in secondary hyperparathyroidism (where we see high PTH but low calcium and vitamin D levels) showed some evidence for impaired cognitive function." (PMID 26010883, 2015). "Secondary hyperparathyroidism in CKD is similar to that observed with persistent exposure to PTH." (PMID 26186634, 2015). "To evaluate the influence of parathyroid mass on the regulation of parathyroid hormone (PTH) secretion, we investigated the relationship between the resected parathyroid gland in total parathyroidectomy and the parathyroid hormone level in hemodialysis patients with secondary hyperparathyroidism." (PMID 26058796, 2015). "However, this association was ascertained in patients on chronic dialysis treatment with long-lasting secondary hyperparathyroidism and very high serum concentration of PTH." (PMID 25113067, 2015). "Furthermore, the PTH serum concentration rose in 2 cases, suggesting secondary hyperparathyroidism in the BP + PPI group." (PMID 25436170, 2014). "As long as we find a negative linear correlation between 25-(OH) D and PTH levels, we can suppose that secondary hyperparathyroidism is linked to vitD deficiency." (PMID 25091406, 2014). "It has been previously reported that of elderly patients who suffered hip fractures and had a serum 25-OH-Vitamin D3 < 12 ng/mL, only half the patients had evidence of secondary hyperparathyroidism, whereas the rest exhibited low to normal levels of PTH or functional hypoparathyroidism." (PMID 24304609, 2013). "After surgical cure, some patients still have elevated levels of PTH which, at least in some of the cases, could indicate a coexistent secondary hyperparathyroidism." (PMID 24026893, 2013). "In this study, we excluded patients with laboratory results indicative of secondary hyperparathyroidism (parathyroid hormone concentrations above the reference range in conjunction with 25-hydroxycholecalciferol levels below the reference range) from our analyses." (PMID 25505674, 2013). "The PTH excess observed in elderly subjects with both primary and secondary hyperparathyroidism may promote weight gain by impeding catecholamine-induced lipolysis." (PMID 23800102, 2013). "Elevated serum phosphorus (P) levels have been linked to increased morbidity and mortality in dialysis patients with secondary hyperparathyroidism (SHPT) but may be difficult to control if parathyroid hormone (PTH) is persistently elevated." (PMID 22863242, 2012). "PTH levels should be determined to diagnose secondary hyperparathyroidism." (PMID 22765843, 2012). "Although 25(OH) D concentrations were similarly low in both groups, secondary hyperparathyroidism (PTH > 6.8 pmol/L) was present in 30.2% of patients with cervical and in 41.3% with trochanteric HF (p = 0.033), and the mean PTH value was significantly higher in the latter group (p = 0.001)." (PMID 22333003, 2012).
secondary hyperparathyroidism (continued). "In the treatment of secondary hyperparathyroidism of chronic kidney disease, calcimimetics - allosteric modulators of the calcium-sensing receptor - inhibit glandular hyperplasia and significantly reduce circulating parathyroid hormone levels." (PMID 23232027, 2012). "Accordingly, both FGF-23 and PTH are involved in the adaptive response to ensuing secondary hyperparathyroidism, with the difference that PTH accentuates the calcitriol deficiency but FGF-23 does not." (PMID 21234310, 2010). "The results of this study demonstrate that circulating IGFBP-4 levels are not influenced by secondary hyperparathyroidism in vitamin D deficiency rickets since IGFBP-4 levels did not change after normalization of PTH with vitamin D treatment." (PMID 21274331, 2010). "Therefore, in treating patients with XLH, the dosage of oral phosphate should be adjusted within an appropriate range when using conventional therapy, based on calcium and PTH levels, to avoid progression from secondary hyperparathyroidism to tertiary hyperparathyroidism." (PMID 40074938, 2025). "In addition, alveolar bone loss was not correlated to serum PTH level in 35 hemodialysis patients with secondary hyperparathyroidism." (PMID 40097880, 2025). "The overall clinical pattern may therefore resemble normocalcaemic hyperparathyroidism, which is described as persistently high PTH levels with normal total and ionised calcium in the absence of known causes of secondary hyperparathyroidism." (PMID 40608198, 2025). "Interestingly, in patients with secondary hyperparathyroidism, there is an increased prevalence of LV-hypertrophy, which was reversed after parathyroidectomy and a subsequent reduction of PTH levels, strengthening the notion that the PTH-1R participates in the CAS and hypertrophic mechanism." (PMID 39941574, 2025). "Therefore, we recommend management of secondary hyperparathyroidism either with pharmacotherapy or surgery with close follow-up of calcium metabolism and serum parathyroid hormone levels along with referral to surgery among refractory secondary hyperparathyroidism to cinacalcet." (PMID 38410685, 2024). "Furthermore, in these patients, a low-calcium diet resulting in secondary hyperparathyroidism and increased PTH levels can also lead to low levels of 25-hydroxyvitamin D due to rapid degradation of the same following increased activity of the enzyme 24,25-hydroxylase." (PMID 38672265, 2024). "Tertiary hyperparathyroidism develops from secondary hyperparathyroidism, in which the glands are subjected to extended and severe stimulation, resulting in some hyperplastic tissue changing into adenomas with hyperfunction and autonomously secreting large amounts of PTH." (PMID 39403580, 2024). "Consequently, the parathyroid glands may increase the production of PTH to balance serum calcium levels, potentially resulting in secondary hyperparathyroidism." (PMID 38714632, 2024). "In addition, elevated PTH may be a marker of secondary hyperparathyroidism, which may result from impaired Ca and vitamin D metabolism after surgery." (PMID 39553143, 2024). "Furthermore, PTH increased with age in mice fed NPD, as has been previously demonstrated in humans and mice, which is suggested to be linked to aging related declines in kidney function, as seen with secondary hyperparathyroidism." (PMID 37079375, 2023). "The use of Rapid Intraoperative parathyroid hormone (Io-PTH) assay during surgery in the management of parathyroid tissue in cases of primary hyperparathyroidism has been proven to be effective, while its utilization in secondary hyperparathyroidism (SHPT) has been rarely reported." (PMID 37231458, 2023). "The mean absolute intact parathyroid hormone reductions that were proportional to baseline intact parathyroid hormone levels is consistent with a mechanism of action involving physiological regulation of intact parathyroid hormone modulated by secondary hyperparathyroidism severity." (PMID 34626363, 2022).
secondary hyperparathyroidism (continued). "Furthermore, in patients with normocalcaemic persistent secondary hyperparathyroidism after kidney transplantation, cinacalcet improved the control of serum PTH without causing calcaemia, or phosphataemia." (PMID 36672533, 2022). "As the main aim of the paper was to evaluate the impact of the serum level of PTH in patients with HF, we did not concentrate on the causes for secondary hyperparathyroidism, which could be the focus of further studies in the context of HF." (PMID 36286286, 2022). "However, PTH concentrations are controlled within a target range of approximately 100–600 pg/mL in only approximately 50% of patients, with reported rates of low PTH (<100 pg/mL) and secondary hyperparathyroidism (SHPT, >600 pg/mL) of approximately 40% and 10%, respectively." (PMID 35634511, 2022). "Kidney dysfunction might induce secondary hyperparathyroidism, resulting in elevated PTH levels." (PMID 36286286, 2022). "Secondary hyperparathyroidism may be a novel mechanism of wasting, corroborating experimental data, and, among chronic dialysis patients, this pathway may be a mediator between elevated PTH levels and mortality." (PMID 34060245, 2021). "Moreover, obesity was positively associated with secondary hyperparathyroidism in adult patients with CKD and in pediatric kidney transplant recipients, while low PTH level was considered as a marker of malnutrition-inflammation complex condition in CKD 5D patients." (PMID 34422722, 2021). "Additionally, PTH possibly blocks leptin secretion in case of severe secondary hyperparathyroidism." (PMID 34422722, 2021). "Because multiple causes of increased PTH secretion have been identified, and because the disorder does not generally warrant immediate surgical action, it is advisable to thoroughly rule out all possible factors contributing to secondary hyperparathyroidism." (PMID 32803112, 2020). "However, severe secondary hyperparathyroidism (that is, characterized by intact PTH serum levels >500 pg/ml or increase ninefold above the normal range) is associated with diminished longitudinal growth and an increased risk of slipped capital femoral epiphysis in paediatric patients with CKD73,74." (PMID 31197263, 2019). "Secondary hyperparathyroidism (sHPT) is a prevailing complication of chronic kidney disease (CKD) caused by the disturbance of calcium, phosphate, and vitamin D, with high concentrations of serum parathormone (PTH) leading to high rates of cardiovascular and bone disease." (PMID 31817421, 2019). "It is therefore difficult to speculate whether either pattern of release had any impact on osteogenic response, a positive effect expected with the pulsatile pattern, or interference with this response with protracted PTH release seen as secondary hyperparathyroidism of postmenopausal women." (PMID 31261978, 2019). "Secondary hyperparathyroidism begins as an adaptive response to maintain serum calcium and phosphorus homeostasis and is characterized by elevated serum concentrations of parathyroid hormone (PTH) mediated in part via the calcium sensing receptor (CaSR) on the parathyroid gland." (PMID 30875390, 2019). "Therefore, people with low calcium levels in blood and a high PTH levels may have secondary hyperparathyroidism, which means that the elevated level of PTH is a normal response of healthy parathyroid glands to another issue like calcium insufficiency." (PMID 31049223, 2019). "Vitamin D Receptor (VDR) Knockout (KO) mice that suffer from a secondary hyperparathyroidism show a series of metabolic disturbances, making it impossible to distinguish between causal effects of VDR and secondary effects caused by pathological PTH concentrations." (PMID 28443031, 2017). "However, a high phosphorus diet reportedly increased bone resorption via secondary hyperparathyroidism, while some studies reported that it influenced bone loss regardless of changes in calcium metabolism and PTH hypersecretion." (PMID 27775655, 2016).
secondary hyperparathyroidism (continued). "Beyond the powerful influence of active vitamin D on bone health through the effective control of secondary hyperparathyroidism, the active vitamin D/VDR complex exerts crucial direct, PTH-independent effects on bone cells to maintain skeletal integrity." (PMID 41515987, 2025). "Secondary hyperparathyroidism (SHPT) is a common, serious complication in patients with chronic kidney disease, characterized by increased parathyroid hormone (PTH) levels, parathyroid hyperplasia, and disruptions in bone mineral metabolism." (PMID 40160292, 2025). "Dialysis: For the dialysis population, we are only aware of two very small prospective cohort studies (n = 16 and n = 13) in patients with osteopenia (PTH > 2× ULN) and patients with secondary hyperparathyroidism (PTH > 500 pg/mL)." (PMID 41303180, 2025). "Secondary hyperparathyroidism (SHPT), a common complication in patients with Chronic kidney disease (CKD), is characterized by excessive secretion of Parathyroid hormone (PTH)." (PMID 40394480, 2025). "The vitamin D status was severely low, 3.5 ng/mL (reference: 30-100 ng/mL), and the parathyroid hormone (PTH) level was high (437 pg/mL), indicating secondary hyperparathyroidism." (PMID 41552144, 2025). "It was remarkable that the parameters of calcium homeostasis before allo-HSCT showed a consistent picture of low to low-normal calcium levels, low 25-hydroxyvitamin D (25-OH-D), and elevated parathyroid hormone (PTH, i.e., secondary hyperparathyroidism)." (PMID 39833182, 2025). "An increased level of PTH is typical of PLWHIV on TDF, and research suggests that secondary hyperparathyroidism is the result of parathyroid gland overcompensation." (PMID 41295288, 2025). "Upon admission, laboratory tests revealed elevated parathyroid hormone (PTH, 650.30 pg/ml) and serum phosphorus (2.85 mmol/L), indicating secondary hyperparathyroidism." (PMID 41368304, 2025). "This study aimed to evaluate the effect of combining paricalcitol with cinacalcet on the levels of intact parathyroid hormone (iPTH) and alkaline phosphatase (ALP) in patients with secondary hyperparathyroidism undergoing maintenance hemodialysis (MHD)." (PMID 40837352, 2025). "The parathyroid hormone (PTH) levels were significantly elevated (457.7 ± 260.7 ng/mL; normal: 11–69 ng/mL), indicating secondary hyperparathyroidism." (PMID 40218268, 2025). "This reduction, in turn, initiates parathyroid hormone (PTH) release, leading to secondary hyperparathyroidism." (PMID 40573160, 2025). "Secondary hyperparathyroidism (SHPT) is a frequent illness in people with CKD and is characterized by high blood intact parathyroid hormone (PTH) levels." (PMID 39791168, 2025). "Secondary hyperparathyroidism with normal BMD was reported in previous studies in adult patients, similarly in our study patients had elevated parathyroid hormone levels with normal and low BMD with normal calcium and phosphorous levels." (PMID 40697385, 2025). "Low vitamin D levels can elevate PTH, making it difficult to distinguish between NPHPT and secondary hyperparathyroidism." (PMID 39040613, 2024). "PTH: Parathyroid hormone; CRF: Chronic renal failure; ESRD: End-stage renal disease; PTH: Parathyroid hormone; SHPT: Secondary hyperparathyroidism; HTRO: High-turnover renal osteodystrophy; iPTH: Intact parathyroid hormone; VDR: Vitamin D receptor." (PMID 39156357, 2024). "Unexpectedly, further investigations revealed a very low vitamin D level, normal calcium levels, and elevated parathyroid hormone (PTH), suggesting secondary hyperparathyroidism." (PMID 38947656, 2024). "The intersection of CKD with disturbances in parathyroid hormone (PTH) signaling emphasizes the derangement of calcium and phosphate homeostasis, often culminating in secondary hyperparathyroidism." (PMID 39484207, 2024).